ALB (albumin)
Diseases named in the same sentence as ALB in open-access papers (continued):
Sharing a sentence is not in itself a finding about the gene and the disease.
heart failure (continued). "Higher blood urea levels were associated with higher tertile serum carbamylated albumin levels, which in turn were positively correlated with heart failure and arrhythmia." (PMID 35448889, 2022). "In 1255 HD patients, greater blood urea levels were associated with serum carbamylated albumin levels, and being in the upper urea tertile was positively correlated with heart failure and arrhythmia." (PMID 35448889, 2022). "In cross-sectional studies with clinical samples, a low serum albumin level was associated with cognitive impairment in hospitalized patients with heart failure, rehabilitation patients with hip fractures, and the oldest patients with Alzheimer’s dementia." (PMID 35160273, 2022). "Many cross-sectional studies in clinical settings have indicated an inverse association between serum albumin and cognitive performance in patients with heart failure, hip fractures, and AD." (PMID 35160273, 2022). "This is not surprising because appetite loss is associated not only with well-known prognostic factors in heart failure (such as serum albumin, and hemoglobin), but also with factors associated with frailty (cognitive dysfunction and ADL)." (PMID 35511913, 2022). "In our research, we found that there is a special population in the linear relationship between albumin and all-cause mortality, and the special population refers to the patients with heart failure complicated with ARDS." (PMID 36171266, 2022). "When assessed with the CONUT score, lymphocytes and total cholesterol are affected by inflammation and medications such as statins, while albumin levels are susceptible to fluid retention in patients with heart failure." (PMID 34835966, 2021). "Previous studies have shown that low albumin levels are strongly associated with cardiovascular disease, heart failure, and mortality in vulnerable populations." (PMID 34268015, 2021). "A prospective study carried out in a cohort of patients with well-characterised heart failure and preserved ejection fraction showed increased urinary albumin excretion was associated with enhanced remodelling of the right and left ventricles." (PMID 32681438, 2021). "Seven variables were independent risk factors, included peritonitis, respiratory failure, cardiac insufficiency, consciousness disturbance, tumor history, albumin level, and creatinine level at the time of admission." (PMID 34015023, 2021). "Low serum albumin is common in patients with heart failure and is associated with increased mortality." (PMID 34869626, 2021). "Low albumin can lead to hypoproteinemia, and it can cause a range of diseases, such as serous effusion, pulmonary edema, heart failure, and more." (PMID 33282887, 2020). "Higher bilirubin and lower albumin concentrations were associated with an increased severity of heart failure both in ICM and in nICM patients." (PMID 31636808, 2019). "Bilirubin and low serum albumin levels have been reported to be associated with elevated mortality rates in patients hospitalized for heart failure." (PMID 28466463, 2017). "Notably, this analysis of MIMIC-III data revealed that albumin administration was associated with increased mortality in heart failure patients with albumin levels ≤ 2.9 g/dL, as determined through stepwise multivariate logistic regression analyses." (PMID 40279952, 2025). "Although AF does notdirectly cause low albumin levels, we speculate that this may be due to thecoexistence of AF and heart failure, where heart failure itself is acondition of inadequate organ perfusion due to cardiac overload." (PMID 40776939, 2025). "Association of creatinine/albumin ratio and 28-day mortality in heart failure patients." (PMID 40703630, 2025). "ACR, albumin-to-creatinine ratio; BP, blood pressure; CrCl, creatinine clearance; eGFR, estimated glomerular filtration rate; HF, heart failure; RCT, randomized controlled trial; RoB 2.0, Cochrane risk of bias tool (version 2.0); SPRINT, Systolic Blood Pressure Intervention Trial." (PMID 41035575, 2025).
heart failure (continued). "This could be shown in 916 heart failure patients with reduced or preserved ejection fraction, where a higher fibrinogen-to-albumin ratio was independently linked to all-cause mortality, irrespective of the heart failure subtype." (PMID 40429565, 2025). "In this research, the study found that giving albumin to patients with heart failure who have low albumin levels was linked to higher adjusted mortality rates during hospitalization and within 28-days, along with prolonged stays in both the hospital and intensive care unit." (PMID 40279952, 2025). "The association between FAR and short-term mortality in heart failure may be due to similar inflammatory disease mechanisms, leading to increased fibrinogen and decreased albumin." (PMID 41030320, 2025). "It has been shown that the albumin–globin ratio, lactate–albumin ratio, blood urea nitrogen–albumin ratio, and fibrinogen–albumin ratio may be important in predicting the risk of heart failure, which is common in the elderly population." (PMID 40944175, 2025). "Ejection fraction, estimated glomerular filtration rate, age, albumin, uricacid, and lactate dehydrogenase are independent risk factors for acute kidneyinjury in heart failure preserved ejection fraction patients after coronaryartery bypass grafting by the random forest model." (PMID 39077338, 2024). "Heart failure contributes to liver congestion, which causes a decrease in albumin synthesis." (PMID 35455574, 2022). "CysC >0.93 mg/dL is associated with heart failure (4.357, 1.132-10.874), but adjusted by age, prevalence of severe pneumonia, as well as serum levels of albumin, glucose, and log NT-proBNP, the association between CysC >0.93 mg/dL and heart failure was not significant in the non-T2DM group." (PMID 34234738, 2021). "Finally, only MetS and low serum albumin were associated with heart failure in multivariate analysis." (PMID 32792012, 2020). "Only MetS and low serum albumin were associated with heart failure in multivariate analysis." (PMID 32792012, 2020). "Also, surgery, application of platinum, albumin level, and heart failure were independent risk factors." (PMID 32939184, 2020). "Low serum albumin was associated with heart failure (OR 0.96; 95CI 0.92–0.99; p = 0.01)." (PMID 32792012, 2020). "The predictive importance of low-grade albuminuria in hypertensive individuals with left ventricular hypertrophy was shown in the LIFE study, where a urinary albumin/ creatinine ratio of > 3.5 mg/mmol was associated with a twofold higher risk of future heart failure." (PMID 20676281, 2009). "Serum albumin is a potent predictor of death or heart failure hospitalization and is an easily overlooked prognostic indicator." (PMID 41602325, 2026). "Upon albumin supplementation, patients with higher albumin levels exhibited higher risks of mortality, shock, heart failure, and pulmonary edema in patients with albumin ≥1.0 g/dL." (PMID 40649163, 2025). "FAR and C-reactive protein to albumin ratio have emerged as prognostic immune biomarkers for a variety of diseases, such as solid tumors, leukemia, hypertension, heart failure, ST-segment elevation, myocardial infarction, and sepsis." (PMID 40510491, 2025). "Nonetheless, certain doctors administer albumin infusions to address resistance to furosemide in heart failure patients with low albumin levels." (PMID 40279952, 2025). "The lactate/albumin ratio (LAR) was related to adverse outcomes in heart failure, myocardial infarction, and acute pancreatitis." (PMID 40538408, 2025). "Patients with heart failure often have a chronic inflammatory state, and the release of inflammatory factors can affect albumin synthesis and stability, leading to decreased albumin levels." (PMID 40104144, 2025). "Due to these factors, patients requiring an NG tube for feeding are often elderly, have comorbidities such as chronic renal dysfunction and heart failure, and exhibit low serum albumin levels." (PMID 41441392, 2025).
heart failure (continued). "Heart failure patients have metabolic disorders, which can lead to increased energy consumption and protein metabolism disorders, affecting albumin levels." (PMID 40104144, 2025). "In contrast, oral supplementation with BCAAs over 28 days has been shown to significantly improve albumin levels in patients with heart failure." (PMID 41003011, 2025). "The ability of albumin to bind nitric oxide and promote endothelial function is essential for maintaining vascular health and treating age-related conditions including heart failure and atherosclerosis." (PMID 40191425, 2025). "In the present case, the male patient’s advanced age, concomitant heart failure with reduced ejection fraction, low serum albumin levels, and stage IV cHL likely contribute collectively to a less favorable prognosis." (PMID 41492631, 2025). "Circulating fibrinogen-to-albumin ratio (FAR) has been proposed as a novel inflammatory biomarker in patients with heart failure and malignant tumor." (PMID 40510491, 2025). "In this study, we tried to understand the relationship between BAR and the poor prognosis of heart failure patients from the perspective of blood urea nitrogen and albumin, respectively." (PMID 40980177, 2025). "The interaction between nutritional status and chronic inflammation contributes to decreased albumin levels in patients with heart failure." (PMID 41030320, 2025). "We estimated the risks of mortality, shock, heart failure, and pulmonary edema in the albumin infusion and control groups." (PMID 40649163, 2025). "The aim of this study was to investigate the correlation between blood urea nitrogen-albumin index (BAR) and 30-day and one-year all-cause mortality in patients with heart failure admitted to the intensive care unit (ICU)." (PMID 40980177, 2025). "Previous studies have found a correlation between low albumin levels and poor prognosis in patients with heart failure." (PMID 40980177, 2025). "Currently, there is no clear evidence supporting the advantages of administering albumin for heart failure." (PMID 40279952, 2025). "The association between red cell distribution width—albumin ratio (RAR) and the risk of all-cause mortality in intensive care unit (ICU) patients with heart failure remains uncertain." (PMID 39901900, 2025). "The HRs for septic shock, cardiogenic shock, hypovolemic shock, heart failure, and pulmonary edema were higher in the albumin infusion group than in the control group." (PMID 40649163, 2025). "The use of albumin has been linked to increased risk-adjusted mortality during hospitalization, as well as prolonged stays in both hospital and ICU settings for patients with heart failure and low levels of serum albumin." (PMID 40279952, 2025). "An increasing number of studies have confirmed that serum albumin levels have important predictive value in the prognosis of heart failure patients." (PMID 39927140, 2025). "The study identified vitamin D as an independently predictive factor of LVEF in heart failure patients and highlighted its potential interaction with uric acid and albumin." (PMID 38792959, 2024). "Research suggests that albumin levels are an independent predictor of new-onset heart failure and in-hospital mortality in patients with acute coronary syndromes (ACS)." (PMID 39416435, 2024). "After the results of LASSO regression models and Cox multivariate analyses, a total of 8 variables were selected, gender, age, poverty income ratio, heart failure, body mass index, albumin, blood urea nitrogen and serum uric acid." (PMID 38600468, 2024). "Our study employed COX regression and LASSO regression, ultimately incorporating eight factors: gender, age, PIR, heart failure, BMI, albumin, blood urea nitrogen and serum uric acid." (PMID 38600468, 2024). "Patients with esophageal cancer with low pretreatment serum albumin levels reportedly have a higher incidence of complications, such as BSIs, respiratory failure, arrhythmias, and heart failure." (PMID 38983366, 2024).
heart failure (continued). "This is a subanalysis of the Spanish Cardiorenal Registry, in which we enrolled 864 outpatients with heart failure and a value of urinary albumin:creatinine ratio (UACR) at the first visit." (PMID 38835512, 2024). "Patientssuffering from heart failure often have low serum albumin due to inflammation andmalnutrition." (PMID 39742221, 2024). "For male patients, older age, lower family income, concomitant heart failure, and underweight status, lower albumin levels, and higher levels of uric acid and blood urea nitrogen were associated with a higher risk of all-cause mortality." (PMID 38600468, 2024). "Cardiovascular mortality and hospitalization due to heart failure in patients with DM with CKD is directly correlates with increasing albumin excretion and falling eGFR." (PMID 39680348, 2024). "As the most abundant protein in human body, the serum albumin < 35 g/L has been demonstrated to be a predictor for short term death as well as heart failure in ACS patients." (PMID 39003493, 2024). "The prognostic value of the uric acid to albumin ratio (UAR) in heart failure (HF) remains underexplored." (PMID 39659906, 2024). "A previous study has mostly considered albumin decline as a riskfactor for patients suffering from heart failure, and patients suffering fromheart failure complicated with hypoproteinemia usually have a poor prognosis." (PMID 39742221, 2024). "Recent MR studies have examined the causal effects of serum albumin concentrations on atrial fibrillation (AF), venous thromboembolism (VTE) and heart failure (HF)." (PMID 38580915, 2024). "Compared to those did not progress to ESKD after incident heart failure (n = 142), participants who progressed to ESKD after heart failure occurrence were younger, had higher HbA1c and higher urine albumin-to-creatinine ratio at baseline." (PMID 38879473, 2024). "It is worth noting that in the occurrence and development of heart failure, serum albumin not only decreases in level, but also changes structurally." (PMID 36824173, 2023). "The correlation of heart failure and inflammation appears to be supported by the decrease in albumin concentration and the rise in other inflammatory biomarkers, such as C-reactive protein (CRP)." (PMID 36669034, 2023). "In people with heart failure with preserved ejection fraction, liver fibrosis with NFS ≥ 1.56 upon inclusion of serum albumin was associated with an increased risk of all-cause mortality." (PMID 36986234, 2023). "Serum albumin and BMI are common nutrition indicators; however, they are affected by dehydration, heart failure, inflammation, and other factors." (PMID 36960208, 2023). "Geriatric nutrition risk index (GNRI) is calculated by considering both the BMI and serum albumin level of the patient, and it has been shown that it can predict the prognosis in patients with heart failure." (PMID 37791200, 2023). "The Prenner SB’s study showed that serum ALB is a strong prognostic factor for heart failure withlower ejection fraction." (PMID 39077558, 2023). "Since both albumin and ALP are also reported to be associated with the prognosis in patients with heart failure respectively, adding these two parameters in calculation formula seems to be helpful for prediction for prognosis in patients with heart failure." (PMID 37087702, 2023). "We emphasized the importance of albumin in short-term death of ICU patients with heart failure and provided theoretical threshold to provide a theoretical basis for the treatment goal." (PMID 36171266, 2022). "Albumin is a protective factor for in-hospital or long-term mortality of patients with heart failure." (PMID 36171266, 2022). "In patients with subarachnoid hemorrhage, the maximum tolerated dosage of albumin was determined by the rate of treatment-related severe or life-threatening heart failure." (PMID 36337861, 2022).
heart failure (continued). "Prevalence and prognostic value of elevated urinary albumin excretion in patients with chronic heart failure: data from the GISSI-Heart Failure trial." (PMID 35137781, 2022). "Previous studies have indicated that the ratio of lactate/albumin (L/A) has predictive value for the prognosis of critically ill patients with heart failure." (PMID 36401181, 2022). "There were differences in gender, primary disease, time on dialysis, hemoglobin, albumin, creatinine, potassium, phosphorus, calcium, total cholesterols, heart failure rate among three groups (P < 0.05)." (PMID 35962178, 2022). "This study developed a cohort prediction model based on 7121 individuals with heart failure to evaluate the short-term mortality and prognostic role of albumin in patients with CHF." (PMID 36171266, 2022). "In univariable regression analyses, age, abscess formation, albumin level at admission, heart failure, uncontrolled infection, systemic embolism, and presence or absence of cardiac surgery when indicated were found to be correlated with all-cause mortality." (PMID 36161622, 2022). "For patients with heart failure, low serum albumin level, high BUN/Cr ratio, or hyperuricemia, clinicians can provide predialysis counseling in advance and consider early creation of vascular access." (PMID 34219598, 2021). "Heart failure, low serum albumin, high BUN/Cr ratio, and hyperuricemia when the eGFR decreased to approximately 20 mL/min/1.73 m2 were independent predictors of early initiation of dialysis." (PMID 34219598, 2021). "Lower albumin concentration is also observed in the elderly and in patients with heart failure due to intestinal edema that disables an adequate albumin absorption." (PMID 34730889, 2021). "To summarize, we have synthesized and developed stable AT1 peptide conjugated albumin nanoparticles to deliver MRN in a targeted manner for heart failure treatment." (PMID 34591850, 2021). "It was suggested that NLR level should be explained with other inflammatory biomarker such as CRP/ALB and heart failure indicator to improve the ability of predicting mortality risk." (PMID 33746575, 2021). "Oral supplementation with branched-chain amino acids was found to improve serum albumin levels in hospitalized patients with heart failure." (PMID 33805128, 2021). "Univariant analysis showed significance for age, serum albumin, heart failure and P. Adjusted model analysis, kept significance for age, serum albumin, P and the percentage of proinflammatory monocytes CD14+/CD16+." (PMID 34300056, 2021). "The analyses also revealed that heart failure, low serum albumin level, high BUN/Cr ratio, and hyperuricemia were independent predictors of early initiation of dialysis." (PMID 34219598, 2021). "A 10-variable model using age, acute heart disease, albumin, body mass index, chronic obstructive pulmonary disease, gender, heart failure, insurance, kidney disease, and shock yielded the best performance (C-statistic, 0.80 [95% CI 0.79–0.80])." (PMID 33812369, 2021). "Our study attempted to identify the predictors of early initiation of dialysis at a relatively high eGFR and found that heart failure, high BUN/Cr ratio, low serum albumin level, and hyperuricemia were associated with early initiation of dialysis." (PMID 34219598, 2021). "It has previously been reported that low albumin levels predict mortality in the general population, as well as in certain groups, such as heart failure patients." (PMID 33152050, 2020). "According to the age-adjusted analysis, heart failure, malignancy, kidney function parameters, and sodium, calcium, albumin, LDH, AST, CRP, ferritin, D-dimer, Hct, WBC and lymphocyte levels were associated with mortality." (PMID 32881976, 2020). "Serum albumin level is an independent predictor of one-year survival in patients with heart failure with preserved ejection fraction." (PMID 32776978, 2020).